BCL2A1 (BCL2 related protein A1)
Diseases named in the same sentence as BCL2A1 in open-access papers (continued):
Sharing a sentence is not in itself a finding about the gene and the disease.
lymphoma (12 papers, 2012 to 2026). A malignant (clonal) proliferation of B- lymphocytes or T- lymphocytes which involves the lymph nodes, bone marrow and/or extranodal sites. "While many solid cancers display upregulation of BCLxL or MCL-1 compared to the respective healthy cells, a basal upregulation of cellular BCL2A1 levels has been described in breast cancer, melanoma, or hematological and lymphoid cancers, such as DLBCL." (PMID 39192247, 2024). "In this case study, the lymphoma cells exhibited high levels of BCL2A1 expression and it was suggested that BFL-1 could play a role in the survival of these cancer cells similar to the role played by BCL-2 in the more common MYC/BCL-2 double-hit lymphomas." (PMID 35900226, 2022). "The distinctive mBL signature consisted of 58 genes, including several target genes of the NF-κB pathway (i.e., BCL2A1, FLIP, CD44, NFKBIA, BCL3, and STAT3) that are known to distinguish activated B-cell-like or germinal center B-cell-like lymphomas." (PMID 26416427, 2015). "However, transgenic BCL2A1 mice do not develop lymphomas, suggesting that either BCL2A1 overexpression is not sufficient for tumorigenesis or BCL2A1 functions differ between mice and humans, as is the case of BCL2A1 cellular distribution." (PMID 23441221, 2013).
chronic lymphocytic leukemia (9 papers, 2007 to 2022). "High expression of BCL2A1 is associated to chemoresistance against fludarabine or etoposide in progressive chronic lymphocytic leukemia cells, in vitro." (PMID 23441221, 2013). "It has been reported that enhanced synthesis of BCL2A1 andBCL-XL are the underlying cause of about 1000-fold greaterresistance of subsets of chronic lymphocytic leukemia cells." (PMID 21637860, 2011). "High BCL2A1 expression has been found to correlate with more severe cases of progressive chronic lymphocytic leukemia, indicating that BCL2A1 contributes to apoptosis resistance." (PMID 23441221, 2013). "BCL2A1, gene encoding a member of the BCL‐2 family protein, it could mediate drug resistance such as asparaginase resistance in B‐ALL, cytarabine and doxorubicin resistance in AML, fludarabine and ABT‐737 resistance in chronic lymphocytic leukemia (CLL) cells." (PMID 35603962, 2022). "Further, while being effective in cancers that depend on BCL2 for survival, such as chronic lymphocytic leukemia (CLL), resistance to ABT-199, as well as other inhibitors of BCL2, can occur through upregulation of other anti-apoptotic proteins such as BCL-XL, BFL1 (BCL2A1), or MCL1." (PMID 32824203, 2020).
diffuse large B-cell lymphoma (9 papers, 2011 to 2024). "The antiapoptotic protein BCL2A1 is highly, but very heterogeneously expressed in Diffuse Large B-cell Lymphoma (DLBCL)." (PMID 39192247, 2024). "Transcriptional profiling recently characterized the tumor microenvironment and host inflammatory response in diffuse large B-cell lymphoma, which expresses BCL2A1." (PMID 23441221, 2013).
acute myeloid leukemia (8 papers, 2012 to 2025). Acute myeloid leukemia (AML) is a group of neoplasms arising from precursor cells committed to the myeloid cell-line differentiation. "Based on our analysis, we detected BCL2A1 in 3 separate signaling pathways, namely, NF-KappaB, Acute Myeloid Leukemia and transcriptional misregulation in cancer." (PMID 34650160, 2021). "In acute myeloid leukemia, BCL2A1 may become a novel therapeutic target for treating FLT3-ITD/D835 mutant AML." (PMID 40707992, 2025). "Besides the alternative reliance on BCL2A1, we highlight inflammation as a common element present across multiple sources of venetoclax ex vivo response modulation in acute myeloid leukemia samples." (PMID 40222279, 2025). "In one small study BCL2A1 mRNA was over-expressed in acute lymphoid leukemia (ALL), acute myeloid leukemia (AML), chronic lymphoid leukemia (CLL), chronic myeloid leukemia (CML), and mantle cell lymphoma tumor cells compared to normal marrow cells." (PMID 23118966, 2012).
lung carcinoma (8 papers, 2011 to 2024). "In particular, SUSD2, CCND2, BCL2A1, and TMEM158 could be potential targets of JFK in human lung cancers." (PMID 27087825, 2016). "Data from Gene Expression Profiling Interactive Analysis (GEPIA) 25 analysis confirmed a significantly positive correlation of MARCKS expression with TNFR, RELA, BCL2A1, CXCL1, RELB or TNF-alpha in lung cancer samples but not in normal lung tissues." (PMID 33754052, 2021).
Sepsis (8 papers, 2019 to 2025). Sepsis is defined as life-threatening organ dysfunction caused by a dysregulated host response to infection. "The BCL2A1 gene is a direct transcriptional target of NF-κB in response to inflammatory mediators and has good diagnostic and prognostic value in sepsis." (PMID 40426888, 2025). "This research demonstrates the impact of IBD on the progression of Sepsis and analyses two DEGs, BCL2A1 and CEBPB, as potential diagnostic biomarkers for both IBD and Sepsis." (PMID 39993996, 2025). "It was revealed that BCL2A1 had good diagnostic and prognostic value for sepsis, and that it can be applied as a potential and novel biomarker for the management of the disease." (PMID 35832273, 2022). "To further verify BCL2A1 as a novel diagnostic biomarker for patients with sepsis, we selected three other sepsis datasets (GSE28750, GSE69528, and GSE100159) to compare the diagnostic accuracy of BCL2A1 and FCGR1A in the disease." (PMID 35832273, 2022). "In conclusion, our study found that BCL2A1 revealed good diagnostic and prognostic value for sepsis." (PMID 35832273, 2022). "Single-cell RNA sequencing analysis detected that FCGR1A and BCL2A1 might be potential biomarkers for sepsis diagnosis and the diagnostic efficacy of BCL2A1 was further validated by ROC curve and DCA." (PMID 35832273, 2022). "The results showed that BCL2A1 had a good diagnostic value in all datasets, which indicated that it might be considered as a potential biomarker for sepsis." (PMID 35832273, 2022). "A mouse model of IBD combined with Sepsis was constructed, and real‐time PCR and western blot validated the expression of BCL2A1 and CEBPB." (PMID 39993996, 2025). "A recent study demonstrated that miR-122 mitigates sepsis-induced liver injury by targeting the BCL2A1 signaling pathway, thereby reducing macrophage apoptosis and alleviating inflammatory responses." (PMID 40135054, 2025). "BCL2A1 has already been regarded as a highly regulated nuclear factor κB (NF‐κB) target gene, and it is also upregulated in Sepsis patients." (PMID 39993996, 2025). "Our study showed that BCL2A1 was significantly upregulated in patients with sepsis at both the tissue- and single-cell levels." (PMID 35832273, 2022). "BCL2A1 was identified as a prognostic biomarker for sepsis patients in our study through LASSO and Random Forest regression analysis." (PMID 35832273, 2022). "BCL2A1 was identified as a promising and novel biomarker for sepsis diagnosis in our study, limitation still exists." (PMID 35832273, 2022). "The LASSO Cox and random forest regression algorithms demonstrated that BCL2A1 was closely related to the prognosis of sepsis." (PMID 35832273, 2022). "In this study, we integrated bulk-RNA sequencing data and scRNA data and identified two biomarkers (FCGR1A and BCL2A1), which were closely related to sepsis and monocyte/macrophage." (PMID 35832273, 2022). "BCL2A1 and CEBPB were identified as potential biomarkers with diagnostic value of IBD and Sepsis." (PMID 39993996, 2025). "Additionally, the ROC analysis confirmed that the expression of BCL2A1 and CEBPB were of great diagnostic value in IBD and Sepsis and." (PMID 39993996, 2025). "This could explain partly why BCL2A1 was significantly increased in patients with sepsis and was primarily expressed in terms of monocytes/macrophages." (PMID 35832273, 2022). "The effect of increasing BCL2A1 expression on monocyte/macrophage cells appears to exert its antiapoptotic function and further exacerbate the imbalance between M1-and M2-like macrophages and eventually worsen the status of sepsis." (PMID 35832273, 2022). "On the other hand, BCL2A1 has rarely been reported in the pathogenesis of sepsis." (PMID 35832273, 2022). "The BCL2A1 gene can be applied as a potential and novel biomarker for the management of sepsis." (PMID 35832273, 2022).
Sepsis (continued). "In addition, to further verify BCL2A1 as a novel biomarker for diagnosing sepsis, we selected three other sepsis datasets to perform ROC curve analysis and DCA." (PMID 35832273, 2022). "Finally, it remains to be explored whether BCL2A1 and CEBPB can be incorporated into existing diagnostic protocols as potential biomarkers for both IBD and Sepsis, with the aim of improving disease detection and prognosis." (PMID 39993996, 2025). "BCL2A1 may, therefore, induce sepsis progression by mediating NF‐κB activation." (PMID 39993996, 2025). "Therefore, we hypothesise that BCL2A1 ASOs or CEBPB ASOs can influence the progression of Sepsis by targeting BCL2A1 and CEBPB in the intestines of mice." (PMID 39993996, 2025). "Finally, FCGR1A and BCL2A1 were found to be considerably increased in the sepsis group." (PMID 35832273, 2022). "To explore the mRNA expression levels of BCL2A1 and CEBPB, we consulted datasets from healthy individuals as well as patients with Sepsis and IBD." (PMID 39993996, 2025). "BCL2A1 and CEBPB expression levels were significantly increased in mice with Sepsis complicated by IBD." (PMID 39993996, 2025). "Five characteristic genes—BCL2A1, CD44, ADGRG1, TGIF1, and ING3—were identified, which enabled the prediction of mortality of sepsis." (PMID 37069215, 2023). "As expected, the DCA results showed that BCL2A1 and FCGR1A yielded similar clinical values in the diagnosis of sepsis." (PMID 35832273, 2022). "The ROC curve analysis revealed that both BCL2A1 and FCGR1A had a high AUC for the diagnosis of sepsis in all three datasets." (PMID 35832273, 2022). "Furthermore, we confirmed that levels of BCL2A1 and CEBPB were elevated in mice with IBD complicated by Sepsis through real‐time PCR and observed that IBD exacerbates the progression of Sepsis." (PMID 39993996, 2025). "Our single-cell sequencing data demonstrated that sepsis marker genes were highly elevated in CD16+ monocytes, including NAP1L1, CFD, BID, BCL2A1, MALAT1, RNH1, and LILRA5 genes." (PMID 39294473, 2024).
prostate carcinoma (7 papers, 2013 to 2025). A carcinoma that arises from epithelial cells of the prostate gland. "Silencing BCL2A1 in prostate cancer decreased cell count, increased apoptosis, and improved cabazitaxel resistance." (PMID 40739397, 2025). "Several published papers have found that NF-κB binds to the promoters of BCL2, BCL2A1, and MCL1 and activates their expression in many cell types, such as prostate cancer cells, esophageal squamous carcinoma cells, and fibrosarcoma cells." (PMID 36853387, 2023).
COVID-19 (6 papers, 2020 to 2023). A disease caused by infection with severe acute respiratory syndrome coronavirus 2. "Meanwhile, CXCL8, S100A8, S100A9, S100A12, FCGR1A, PADI4, and BCL2A1 showed significant increases in severe COVID-19 when compared with mild COVID-19 (p <0.05)." (PMID 36159873, 2022). "Interestingly, the results were consistent with those in COVID-19; 27 of the IRGs were highly expressed in myeloid cells, except Icam1, Lyn, Cybb, Casp1, Gbp1, Vnn2, Socs3, Bcl2a1 and Lcn2 genes." (PMID 36817436, 2023).
hepatocellular carcinoma (6 papers, 2013 to 2025). A malignant tumor that arises from hepatocytes. "RETRACTION: X. Ma, Z. Mao, J. Zhu, H. Liu, F. Chen, lncRNA PANTR1 Upregulates BCL2A1 Expression to Promote Tumorigenesis and Warburg Effect of Hepatocellular Carcinoma through Restraining miR-587, Journal of Immunology Research, 2021." (PMID 40351571, 2025). "Previous studies reported that there was an association of high BCL2A1 expression with metastatic melanoma and hepatocellular carcinoma, which prompted us to consider the clinical function of BCL2A1 in ovarian cancer." (PMID 34572804, 2021). "Other genes upregulated were BCL2A1, an anti-apoptotic player, usually implicated in cancer progression, as well as YWHAZ, YWHAH, and IRS2, which participates in the development of insulin resistance as well as hepatocellular carcinoma." (PMID 36612019, 2022).
lung adenocarcinoma (5 papers, 2006 to 2026). A carcinoma that arises from the lung and is characterized by the presence of malignant glandular epithelial cells. "It has been shown that shear regulators can selectively induce BCL2A1-dependent tumor cells, leading to apoptosis of NSCLC cells, while targeting the intrinsic pathway of BCL-2-related apoptosis can effectively treat lung adenocarcinoma." (PMID 34308964, 2021). "In the TCGA dataset of lung adenocarcinoma, expression of MCL1, BCL2, BCL2L2, and BCL2A1 was significantly higher in non-tumor relative to tumor cells." (PMID 39122703, 2024).
multiple myeloma (5 papers, 2011 to 2022). "From a gene transcript expression analysis of eight primary multiple myeloma patient samples that relapsed after chemotherapy, BCL2A1 was identified as the most frequently increased factor, suggesting its therapy resistant role in multiple myeloma." (PMID 35900226, 2022).
gastric cancer (4 papers, 2011 to 2023). A primary or metastatic malignant neoplasm involving the stomach. "When first identified, human BCL2A1 mRNA was found overexpressed in stomach cancer compared to normal tissue, indicating a possible function of BCL2A1 also in solid tumours." (PMID 26556430, 2014).
oral squamous cell carcinoma (4 papers, 2010 to 2022). "BCL2A (BCL2-related protein A1) up-regulated in epithelial and stromal fractions is associated with anti-apoptosis, it was described with a significant increased expression in the SP cells in human oral squamous cell carcinoma and related to cellular survival." (PMID 20585575, 2010). "A recent study reported that IDO suppresses apoptosis by repressing BCL2A1 expression in oral squamous cell carcinoma." (PMID 36253713, 2022). "Transcriptional profiling indicated that BCL2A1 is highly expressed in squamous cell carcinoma of the skin and that, later on, BCL2A1 was observed to be overexpressed in oral squamous cell carcinoma." (PMID 26556430, 2014). "It has been reported that the knockdown of AIM2 downregulates nuclear factor κB (NF-κB) expression, resulting in the suppression of cell growth and apoptosis in oral squamous cell carcinoma 26, while the transcription factor NF-κB binds to the BCL2A1 promoter induces its mRNA transcription." (PMID 33391539, 2021).
ovarian carcinoma (4 papers, 2021 to 2023). A malignant neoplasm originating from the surface ovarian epithelium. "Our findings were verified in human ovarian cancer tissues, where BCL2A1 was associated with advanced and high-grade metastatic ovarian cancer." (PMID 34572804, 2021). "The findings reported herein clearly verify that metastatic ovarian cancer cells require higher BCL2A1 expression, facilitating tumor survival and progression in harsh tumor microenvironments (TMEs) with multiple stressful challenges." (PMID 34572804, 2021). "In contrast, knockdown of BCL2A1 elevated the cleavage of PARP in ovarian cancer cells under various physiological stress conditions." (PMID 34572804, 2021). "Here, we show that a BCL2 family member, BCL2A1, acts as a stress-inducible factor that protects ovarian cancer cells against hypoxia-induced cell death by transcriptome profiling analysis." (PMID 34572804, 2021). "Functionally, BCL2A1 enhanced the foci formation ability of ovarian cancer cells in a stress-conditioned medium, colony formation in an ex vivo omental tumor model, and tumor dissemination in vivo." (PMID 34572804, 2021). "We thus performed a soft agar assay to test the anchorage-independent colony formation ability of BCL2A1 in ovarian cancer cells." (PMID 34572804, 2021). "The prompt initiation and progressive reduction of BCL2A1 expression by various biological stressors indicated an auto-regulation system of BCL2A1 expression in ovarian cancer cells." (PMID 34572804, 2021). "Immunohistochemical (IHC) analysis using a commercial ovarian cancer tissue array (OV481) was subsequently performed to confirm the BCL2A1 expression pattern in clinical ovarian cancer specimens." (PMID 34572804, 2021). "By analyzing The Cancer Genome Atlas (TCGA) datasets, we found a 4-fold increase in the BCL2A1 mRNA levels in ovarian cancer samples compared with normal ovary samples." (PMID 34572804, 2021). "In this study, we identified a BCL2 family member, BCL2A1, as an inducible gene through genome-wide transcriptome profiling using the comparison of ovarian cancer cells treated with hypoxia vis-à-vis normoxia." (PMID 34572804, 2021). "As expected, overexpression of BCL2A1 in ovarian cancer cells markedly prevented cleavage of PARP and Caspase-3 in ovarian cancer cells exposed to serum starvation, hypoxia, or anoikis-mediated stresses." (PMID 34572804, 2021). "Consistently, BCL2A1 showed higher expression levels not only in advanced and metastatic ovarian tumors but also in metastatic ovarian cancer cells in ascites/lavage clinical samples." (PMID 34572804, 2021). "Given that ovarian cancer cells also suffer from growth factor deprivation, the effect of BCL2A1 on cell growth under low serum culture conditions (0.5% FBS) was also determined." (PMID 34572804, 2021). "Our findings showed that NF-ĸB p65 (RELA) but not HIF-1α had four putative binding sites on the promoter of BCL2A1, indicating that NF-κB signaling was the upstream inducer of BCL2A1 in ovarian cancer cells." (PMID 34572804, 2021). "The upregulated BCL2A1 was frequently found in advanced metastatic ovarian cancer cells, suggesting its clinical relevance in ovarian cancer metastatic progression." (PMID 34572804, 2021). "The results showed that significantly higher expression of BCL2A1 was observed in ovarian cancer cells isolated from lavage or ascites than in those isolated from primary ovarian tumors." (PMID 34572804, 2021). "To confirm the expression patterns of BCL2A1 in different ovarian cancer cells after hypoxia treatment (0.5% O2), we performed qPCR analysis on OVCA433, ES-2, and A2780cp cells." (PMID 34572804, 2021). "The co-localization signals between BCL2A1 and mitochondria were further enhanced by ~20% when ovarian cancer cells were co-cultured in low serum (0.5% FBS), glucose-free, and hypoxia-mediated stress conditions for 4 h." (PMID 34572804, 2021).